SUCLG1 (succinate-CoA ligase GDP/ADP-forming subunit alpha)
Diseases named in the same sentence as SUCLG1 in open-access papers:
SUCLG1 is named in the same sentence as 42 diseases in open-access papers, as found by Europe PMC text mining. Sharing a sentence is not in itself a finding about the gene and the disease. The quoted sentences say what the papers report.
mitochondrial DNA depletion syndrome (6 papers, 2019 to 2026). The mitochondrial DNA (mtDNA) depletion syndrome (MDS) is a clinically heterogeneous group of mitochondrial disorders characterized by a reduction of the mtDNA copy number in affected tissues without mutations or rearrangements in the mtDNA. "This study aimed to summarize the genetic variants and clinical characteristics of mitochondrial DNA depletion syndrome (MDS) associated with SUCLG1 mutations in children from China." (PMID 42187506, 2026). "Mutations in the SUCLG1 gene have been linked to mitochondrial DNA depletion syndromes (MDDSs), characterized by severe metabolic dysfunctions." (PMID 39941711, 2025). "The succinate-CoA ligase GDP-forming beta subunit (SUCLG2) has been implicated in the SUCLG1-related mitochondrial DNA depletion syndrome affecting brain and skeletal muscle tissues." (PMID 30606113, 2019). "Human inborn SUCLG1 mutations have been clinically linked to mtDNA depletion syndrome with an unknown mechanism." (PMID 38649537, 2024). "Our study expands the spectrum of SUCLG1 variants involved in mitochondrial DNA depletion syndrome." (PMID 35762302, 2022).
leukemia (4 papers, 2022 to 2025). A malignant (clonal) hematologic disorder, involving hematopoietic stem cells and characterized by the presence of primitive or atypical myeloid or lymphoid cells in the bone marrow and the blood. "AML-derived mutations of FMS-like tyrosine kinase 3 (FLT3) upregulated SUCLG1 to induce POLRMT hyposuccinylation, resulting in enhanced mitobiogenesis and leukemia progression." (PMID 38649537, 2024). "In line, genetic depletion of POLRMT or SUCLG1 significantly delays disease progression in mouse and humanized leukemia models." (PMID 38649537, 2024). "To test this, we stably expressed two different short-hairpin RNAs (shRNAs) against SUCLG1 in human leukemia cells." (PMID 38649537, 2024). "We further investigated the relationship between SUCLG1 and leukemia development in TCGA AML dataset." (PMID 38649537, 2024). "Specifically, leukemia-promoting FMS-like tyrosine kinase 3 (FLT3) mutations modulate nuclear transcription and upregulate SUCLG1 expression to reduce succinyl-CoA and POLRMT succinylation, resulting in enhanced mitobiogenesis." (PMID 38649537, 2024). "Previous studies have linked SUCLG1 to various metabolic disorders and non-hepatic cancers, particularly leukemia, suggesting its potential as a therapeutic target." (PMID 39941711, 2025). "We next tested the metabolic role of SUCLG1 in leukemia cells." (PMID 38649537, 2024). "Importantly, SUCLG1 is a key regulator of mtDNA replication and transcription, targeting SUCLG1 would be beneficial in treating leukemia and solid tumors that are highly dependent on mitochondria." (PMID 38649537, 2024). "Together, SUCLG1 supports the proliferation of leukemia cells." (PMID 38649537, 2024). "SUCLG1 may have functions other than modulating POLRMT succinylation to support leukemia cell proliferation." (PMID 38649537, 2024). "Next, we tested the regulation of SUCLG1 by FLT3 in human leukemia cells." (PMID 38649537, 2024). "SUCLG1-mediated POLRMT hyposuccinylation maintains mtDNA transcription, mitochondrial biogenesis, and leukemia cell proliferation." (PMID 38649537, 2024). "Depleting SUCLG1 in MV411 cells re-expressing POLRMTWT significantly delayed leukemia development, while a milder inhibitory effect was observed in leukemia model established with POLRMTK622R mutant." (PMID 38649537, 2024). "Together, SUCLG1 and POLRMT are essential for mutant FLT3-driven leukemia." (PMID 38649537, 2024).
breast carcinoma (3 papers, 2016 to 2026). "For ACSM3, ECH1, and SUCLG1, no prior association with breast cancer has been reported." (PMID 41517855, 2026).
Cirrhosis (2 papers, 2016 to 2025). A chronic disorder of the liver in which liver tissue becomes scarred and is partially replaced by regenerative nodules and fibrotic tissue resulting in loss of liver function. "However, one gene Suclg1 was considerably downregulated in the cirrhosis versus up-regulation in the normal group." (PMID 27357559, 2016).
epilepsy (2 papers, 2017 to 2023). A brain disorder characterized by episodes of abnormally increased neuronal discharge resulting in transient episodes of sensory or motor neurological dysfunction, or psychic dysfunction. "Hypertrophic cardiomyopathy and liver involvement were exclusively found in patients with SUCLG1 mutations, whereas epilepsy was much more frequent in patients with SUCLA2 mutations compared to patients with SUCLG1 mutations." (PMID 28324239, 2017). "Epilepsy has also been described, more commonly in association with SUCLA2 than SUCLG1 gene mutations; however, none of the patients in this series developed epileptic seizures or evident encephalopathy." (PMID 38073635, 2023).
hepatic cancers (2 papers, 2024 to 2025). "This downregulation also correlated with poorer patient survival, suggesting that SUCLG1 may be a potential therapeutic target for age-associated liver cancers." (PMID 39941711, 2025).
kidney cancer (2 papers, 2020 to 2021). Primary or metastatic malignant neoplasm involving the kidney. "HMGCL led to abnormal metabolism of ketone bodies in kidney cancer, and SUCLG1 led to the coupling of succinyl-CoA hydrolysis with the synthesis of either ATP or GTP during the TCA cycle." (PMID 34094922, 2021). "Kidney cancer patient with SUCLG1, GLDC, SLC12A1, PCK2, ATP1A1 and PDHA1 alteration showed highest mortality." (PMID 32699530, 2020). "Here, we showed that SUCLG1 was significantly down regulated in both human kidney cancer tissues and cell lines." (PMID 32699530, 2020).
mitochondrial DNA depletion syndrome 9 (2 papers, 2022). Fatal infantile lactic acidosis with methylmalonic aciduria is a rare neurometabolic disease characterized by infantile onset of severe encephalomyopathy, lactic acidosis and elevated methylmalonic acid urinary excretion. "Mitochondrial DNA depletion syndrome 9 (MTDPS9) is caused by biallelic SUCLG1 variants." (PMID 35762302, 2022). "Variants in SUCLG1, the nuclear gene encoding the alpha subunit of the SCS enzyme playing a pivotal role in maintaining mtDNA integrity and stability, are associated with mitochondrial DNA depletion syndrome 9 (MTDPS9)." (PMID 35762302, 2022).
renal carcinoma (2 papers, 2020 to 2025). A carcinoma arising from the epithelium of the renal parenchyma or the renal pelvis. "In order to clarify the mechanisms of SUCLG1, PCK2, and GLDC in renal cancer, this study further focused on their proliferation, migration, invasion, and cell cycle of renal cancer cells through cell biology experiments." (PMID 32699530, 2020). "In conclusion, the experimental results showed that over expression of SUCLG1, PCK2, and GLDC can inhibit the progression of renal cancer cells." (PMID 32699530, 2020). "In this study, we analyzed the databases of GEO, TCGA, GEPIA, Oncomine, and found that six genes (SUCLG1, PCK2, GLDC, SLC12A1, ATP1A1, and PDHA1), are related to the survival prognosis of patients with renal cancer." (PMID 32699530, 2020). "In order to clarify the molecular mechanism of these genes, we selected 3 molecules (SUCLG1, PCK2, GLDC) that have not previously been studied in renal cancer, and conducted in vitro experiments on them." (PMID 32699530, 2020).
acute myeloid leukemia (1 paper, 2023). Acute myeloid leukemia (AML) is a group of neoplasms arising from precursor cells committed to the myeloid cell-line differentiation. "Increased SUCLG1 expression in acute myeloid leukemia patients is associated with a decreased percent survival and identifies as a risky prognostic gene." (PMID 37601653, 2023).
age (1 paper, 2025). A temporal measurement of the time period elapsed since an identifiable point in the life cycle of an organism. "The crucial role of SUCLG1 in metabolic homeostasis and its inhibition with age and in malignant liver disease stages present a rationale for further elucidating the ‘driving’ role of SUCLG1 in age-associated cancers." (PMID 39941711, 2025).
Atrophy (1 paper, 2021). Any weakening or degeneration, especially through lack of use. "The other proteins Gapdh, Cat, Vegfa, Decr1, Cs, and Suclg1 are mostly important links in redox and energy metabolism pathways, and they may be potential targets in denervated muscle atrophy for treatment." (PMID 34193880, 2021).
Birk-Landau-Perez syndrome (1 paper, 2023). "Normal neuroimaging was observed in 12 (6.9%) individuals, including individuals with galactose-1-phosphate uridylyltransferase deficiency, SUCLG1 deficiency, Lesch-Nyhan syndrome, OPA3 deficiency, phosphatidylserine flippase deficiency, and Birk-Landau-Perez syndrome." (PMID 37810989, 2023).
cardiomyopathy (1 paper, 2020). A disease of the heart muscle or myocardium proper. "Accumulation of succinylated HADHA could lead progressively to reduced β-oxidation, built-up of acyl-carnitines, and ultimately contribute to cardiomyopathy, a pathology that has been reported in cases of SUCLG1 deficiency." (PMID 33230181, 2020).
glioma (1 paper, 2017). A benign or malignant brain and spinal cord tumor that arises from glial cells (astrocytes, oligodendrocytes, ependymal cells). "We have also identified a four RBP (NOL3, SUCLG1, HERC5 and AFF3) signature, having a unique expression pattern in glioma stem-like cells (GSCs), to be an independent poor prognostic indicator in GBM." (PMID 28035070, 2017).
Hydrocephalus (1 paper, 2023). Hydrocephalus is an active distension of the ventricular system of the brain resulting from inadequate passage of CSF from its point of production within the cerebral ventricles to its point of absorption into the systemic circulation. "Early-onset hydrocephalus should be added to the clinical findings associated with SUCLG1-related MDDS." (PMID 38073635, 2023).
hypothyroidism (1 paper, 2021). Abnormally low levels of thyroid hormone. "These DEPs including Pygl, Pklr, Pc, Ehhadh, Acox1, Fasn, Acly, Acsl1, Acsl5, Pgm1, Suclg1, Gpt, Idh1, Fh, and Adh1 maight be as target proteins of AMR and its fractions for hypothyroidism." (PMID 33959028, 2021).
liver diseases (1 paper, 2025). "Tissue biopsies with molecular phenotypes related to liver disease progression show downregulated mRNA levels of SUCLG1, most drastically observed in the malignant liver disease stages of HCC and CC." (PMID 39941711, 2025). "We then selected three of the top upregulated or downregulated genes in aging for further studies in liver diseases/cancer: B2M (upregulated with age), C1qA (upregulated with age), and SUCLG1 (downregulated with age)." (PMID 39941711, 2025). "By analyzing tissue samples from various liver disease stages, we found decreased levels of the gene SUCLG1 in advanced liver diseases, particularly in HCC and CC." (PMID 39941711, 2025).
malaria (1 paper, 2020). Malaria is a serious and sometimes fatal disease caused by a parasite that commonly infects a certain type of mosquito which feeds on humans. "All human proteins in this cluster were known to be drug targets and there were 19 associations of these five human proteins (SUCLG1, SDHA, SDHB, SDHC, and SDHD) and five malaria proteins (PVX_096130, PVX_123265, PVX_003675, PVX_113540, and PVX_003575)." (PMID 32075230, 2020).
methylmalonic acidemia (1 paper, 2023). A genetically heterogenous inherited disorder characterized by abnormalities in the metabolism of lipids and proteins. "In a Chinese study of 310 isolated methylmalonic acidemia patients, approximately 3.2% of patients were found to harbor a mutation in SUCLG1, while only 0.9% of them were secondary to the SUCLA2 mutation." (PMID 38073635, 2023).
Methylmalonic aciduria (1 paper, 2023). Increased concentration of methylmalonic acid in the urine. "SUCLG1-related MDDS 9 (encephalomyopathic type with methylmalonic aciduria, OMIM #245400) and SUCLA2-related MDDS 5 (encephalomyopathic type with or without methylmalonic aciduria, OMIM #612073) are rare subtypes of MDDS caused by biallelic pathogenic variations in the SUCLG1 and SUCLA2 genes." (PMID 38073635, 2023).
mitochondrial encephalomyopathy (1 paper, 2022). A heterogenous group of disorders characterized by alterations of mitochondrial metabolism that result in muscle and nervous system dysfunction. "Here, we present our findings in a male infant with mitochondrial encephalomyopathy, which could be attributable to compound heterozygous variants in the SUCLG1 gene." (PMID 35762302, 2022).
myocardial infarction (1 paper, 2024). Gross necrosis of the myocardium, as a result of interruption of the blood supply to the area, as in coronary thrombosis. "Ventricular expression of 10 central MitoDEGs (Aco2, Atp5a1, Ndufs3, Ndufv1, Cyc1, Suclg1, Sdha, Sdhb, Cs, and Ndufs2) was verified in a mouse model of myocardial infarction using PCR." (PMID 39775580, 2024).
prostate carcinoma (1 paper, 2018). A carcinoma that arises from epithelial cells of the prostate gland. "Most of the TCA enzymes are upregulated during the first metabolic shift in prostate cancer, and then either stay upregulated (CS, FH) or are downregulated (e.g. ACO2, OGDH, and SUCLG1) during the second shift." (PMID 29563510, 2018).
tumor (8 papers, 2019 to 2025). "It has been shown in certain cancers that SUCLG1 becomes downregulated in tumor tissue, even though the remaining TCA cycle components are upregulated, which indicates additional unexplored functions of SUCLG1." (PMID 40563592, 2025). "On the contrary, succinyl‐CoA synthetase subunit alpha (SUCLG1), involved in hydrolysis of succinyl‐CoA, was less expressed in myeloid cells compared with tumor cells." (PMID 36587392, 2023). "In our study, clinicopathological parameter sage, tumor stage, lymphatic, hematogenous metastases and SUCLG2, SUCLG1, ACLY, SUCLG2P2, ATIC and ACO2 genes were found to be associated with survival in univariable or multivariate analysis." (PMID 34589110, 2021). "Genes and proteins regulating the TCA cycle (PDHA1, SUCLG2, SUCLG1, and IDH2) as well as mitochondrial function (VDAC1, MRPS31, LARS2, OPA1, and MTIF2) showed higher transcripts and protein levels in Wnt‐high compared with Wnt‐low tumor entities." (PMID 35904277, 2022). "Thus, targeting SUCLG1, PCK2, GLDC protein may be a useful strategy to inhibit tumor progression." (PMID 32699530, 2020).
cancer (6 papers, 2011 to 2025). A tumor composed of atypical neoplastic, often pleomorphic cells that invade other tissues. "Pan-cancer ranking of ETC correlation coefficients revealed that SUCLG1 was strongly associated with ETC gene expression across various cancers." (PMID 38649537, 2024). "Potential anti-cancer therapeutic strategies should target a boost in SUCLG1 activity and/or expression." (PMID 39941711, 2025). "Here, we report that expression of tricarboxylic acid cycle enzyme succinate-CoA ligase SUCLG1 strongly correlates with ETC genes across various TCGA cancer transcriptomes." (PMID 38649537, 2024). "Transcriptomes of cancer cell line encyclopedia revealed that SUCLG1 expression showed a significantly positive correlation with MRPL45." (PMID 38649537, 2024). "SUCLG1 showed a positive correlation with other ETC-correlated metabolic genes in the majority of TCGA cancer types (Fig. EV1F)." (PMID 38649537, 2024). "The positive correlation of SUCLG1 expression with electron transport chain (ETC) components across numerous cancers suggests that SUCLG1 and SIRT5 influence POLRMT activity and mitochondrial biogenesis in non-AML cancers." (PMID 38724759, 2024). "We performed pan-cancer correlation analysis of TCGA transcriptomes and found that, among mitochondrial metabolic genes, SUCLG1 strongly showed a positive relation with ETC gene expression." (PMID 38649537, 2024). "SUCLG1 showed positive ETC correlations in most types of cancers." (PMID 38649537, 2024). "Although FLT3 wild-type and mutant cancers present with comparable sensitivity to venetoclax, the levels and activity of SUCLG1, SIRT5, and POLRMT and the potential synergy between venetoclax and SIRT5 inhibitors should be further examined in FL3-IDT AML cases." (PMID 38724759, 2024). "For example, human cytochrome c1, whose gene is regulated by E2F, participates in an electron transport chain and the mitochondria pathway of apoptosis whereas a similar set of electron transport-related genes (COX8, CYB5-M, CYP51A1, FDXR and SUCLG1) were found to be E2F4-bound in cancer cell lines." (PMID 22076139, 2011). "Together, SUCLG1 connects succinyl-CoA with POLRMT succinylation to modulate mitochondrial function and cancer development." (PMID 38649537, 2024).
mitochondrial disease (4 papers, 2013 to 2020). "Mutations in SUCLA2 or SUCLG1 cause an incurable, progressive childhood-onset mitochondrial disease characterized by a progressive encephalomyopathy." (PMID 33230181, 2020). "Three patients had a mitochondrial disease linked to a large mtDNA deletion (patient P02) or to mutations in POLG (patient P04) or SUCLG1 (patient P06)." (PMID 26742794, 2016). "Also, patients with mitochondrial diseases affecting muscle argue against this (TK2, SUCLA2, SUCLG1, RRM2B, DGUOK, and TYMP)." (PMID 30538797, 2018).
infection (1 paper, 2023). The state of being infected such as from the introduction of a foreign agent such as serum, vaccine, antigenic substance or organism. "Additionally, the TCA cycle genes assessed presented the described decrease of expression starting at day post infection 3 and continued downregulated up to day post infection 8, including CS, Ogdh, and Suclg1 or day post infection 4, as observed in Sdhb." (PMID 37679643, 2023).
neurodegenerative disease (1 paper, 2023). A disorder of the central nervous system characterized by gradual and progressive loss of neural tissue and neurologic function. "Interestingly, mtDNA is well documented to play a role across neurodegenerative diseases, including but not limited to AD, PD, and ALS, suggesting that SUCLG1 may be an interesting gene to further look at in the context of neurodegeneration." (PMID 37834458, 2023).
SUCLG1 also shares sentences with these, for which no sentence is quoted: lactic acidosis (2 papers); colorectal cancer (1); COVID-19 (1); Encephalopathy (1); epileptic seizures (1); Hepatitis (1); hypertrophic cardiomyopathy (1); ischemia (1); Lesch-Nyhan syndrome (1); lung carcinoma (1); metabolic disorders (1); neonatal encephalopathy (1); ophthalmoplegia (1).